APP (amyloid beta precursor protein)
Diseases named in the same sentence as APP in open-access papers (continued):
Sharing a sentence is not in itself a finding about the gene and the disease.
neuroblastoma (continued). "The elevated phosphorylation of CDK17 and CDK18 was recently identified in a neuroblastoma cell line expressing amyloid precursor protein (APP)." (PMID 37568654, 2023). "This agrees well with Laulagnier and collaborators who reported the presence of ηCTF in exosomes purified from primary cortical neurons or neuroblastoma N2a cells overexpressing APP wild-type." (PMID 36930302, 2023). "Evidence that T3 reduces β-amyloid precursor protein (APP) expression in neuroblastoma cells had also been reported, and that T3 negatively regulated APP gene expression." (PMID 36897166, 2023). "Another in vitro investigation found that when neuroblastoma cells (N2a-APP/Swe) were exposed to PM, their APP processing increased." (PMID 38173557, 2023). "In LAN5 neuroblastoma cells, metformin increased APP and presenilin levels, which raised APP cleavage and intracellular accumulation of Aβ." (PMID 36909158, 2023). "According to some in vitro studies, CBD increases the Aβ amyloid protein’s proteolytic pathway on SHY5YAPP+ cells (a neuroblastoma cell line) by inducing APP ubiquitination, which boosts cell viability." (PMID 36771595, 2023). "Another example is the amyloid precursor protein (APP) on exosomes derived from neuroblastoma cells specifically targeting neurons." (PMID 38002256, 2023). "Our study demonstrates that astrocyte-derived human ApoE is present at APP-processing sites, with co-localization of ApoE and human Aβ/APP-βCTF in neurons and neuroblastoma cells." (PMID 37290814, 2023). "In this way, it has been detailed that transient overexpression of APP in N2a cells (murine neuroblastoma cell line) prevents the translocation of β-Catenin to the cell nucleus and, therefore, the transcription of Wnt target genes." (PMID 37834082, 2023). "MiR-153 negatively regulates APP expression in human neuroblastoma cells, mouse models, and primary human fetal brain cultures." (PMID 38003448, 2023). "In the present study, we found that depletion of Pon1 upregulated APP in the Pon1−/−5xFAD mouse brain and in mouse neuroblastoma N2a-APPswe cells." (PMID 36899882, 2023). "This study has investigated the effects of hypolipidemic agents fenofibrate, and the flavonoids–naringenin and diosmetin–on apoE4-induced APP processing in rat neuroblastoma cells stably transfected with human wild-type APP 695 (B103-hAPP695wt)." (PMID 38204816, 2023). "Compound 5 reduced Ab formation in neuroblastoma cells transfected with amyloid precursor protein (APP) constructs." (PMID 36299886, 2022). "For our cell-based studies, we investigated the effects of ARV-825 on Aβ levels and APP processing in the human neuroblastoma H4-APP751 model, a previously reported cell model stably overexpressing APP." (PMID 35248531, 2022). "To dissect the effect of Rubicon in a neuronal context, we depleted Rubicon in a neuroblastoma cell line expressing APP, finding a significantly increased release of APP to the cellular medium." (PMID 35740989, 2022). "In one study, treating mouse neuroblastoma cells expressing APP with cilostazol and resveratrol resulted in Aβ reduction." (PMID 36230925, 2022). "The dramatic increase in amyloidogenic processing of APP induced by holo-Lf was dose- and time-dependent in the human neuroblastoma line." (PMID 34400772, 2021). "The impact of holo-Lf binding to APP on amyloidogenic processing was examined in both mouse primary cultures and a human neuroblastoma line." (PMID 34400772, 2021). "To assess the role FAIM plays in prevention of Aβ aggregation, we employed an APP-overexpression system using Neuro 2A cells, a mouse neuroblastoma." (PMID 34970117, 2021). "CRAM-1 blocks proteasomal degradation of ubiquitinated proteins and thus promotes aggregation and SERF2 promotes aggregation of Aβ in human neuroblastoma cells overexpressing APP (amyloid precursor protein)." (PMID 33713180, 2021).
neuroblastoma (continued). "Overexpression of a familial AD-causative amyloid β precursor protein (APP) mutant, V642I-APP, caused the death in SH-SY5Y neuroblastoma cells and the co-incubation with recombinant CLSP suppressed the death." (PMID 33441550, 2021). "To investigate the relationship between APP O-GlcNAcylation and APP endocytosis, we tested the effects of insulin on neuroblastoma SH-SY5Y cells overexpressing APP and BACE1, and cultured rat hippocampal neurons." (PMID 34940409, 2021). "Overexpression of APP in SH-SY5Y neuroblastoma cells, and the overexpression of the C-terminal 100 residue fragment of APP in the brains of transgenic mice, lowered iron levels." (PMID 33219130, 2021). "Applying SILAC proteomics to SH-SY5Y human neuroblastoma cells, we confirmed the downregulation of APP and αSYN by Posiphen treatment." (PMID 34959389, 2021). "To further explore the contribution of APP-derived CTFs to mitochondrial dysfunctions, we used the neuroblastoma stable and inducible cell line expressing C99 fragment only." (PMID 33079262, 2021). "Decreased levels of Drp1 have also been noted in the M17 neuroblastoma line overexpressing wild type APP, and post-mortem tissue, as well as in both sporadic and familial AD patient fibroblasts, though this is not consistent." (PMID 33440662, 2021). "Decreased OPA1 has been noted in the M17 human neuroblastoma line, overexpressing wild type APP, although OPA1 and the mitofusins were found to be increased in HEK293 cells, an embryonic kidney cell line, when human tau was overexpressed." (PMID 33440662, 2021). "In concert with these studies, ChIP experiments have shown that Aβ binds the APP promoter, and in SH-SY5Y neuroblastoma cells, Aβ exposure leads to an increase in APP transcription." (PMID 34572474, 2021). "We previously reported on a prion-like clonal line of AD Swedish-mutant APP N2a neuroblastoma (SWE) cells that consistently produce and maintain intracellular aggregates of Aβ." (PMID 34272583, 2021). "Another study showed that EVs isolated from these APPSwe-expressing neuroblastoma N2a cells contain APP, α-CTF, β-CTF and Aβ1–40/42." (PMID 33203181, 2020). "To validate that ubiquitination is indeed impaired in the APP 5R mutant, we co-expressed His-tagged ubiquitin together with HA-tagged APP WT and APP 5R in neuroblastoma (N2a) cells." (PMID 32065241, 2020). "In neuroblastoma N2a cells expressing the Swedish mutant form of APP (APPSwe), a minor fraction of the Aβ peptides present in MVBs is released in association with EVs." (PMID 33203181, 2020). "Overexpression of 17A, 38A, NDM29, and 51A in neuroblastoma cell lines increased secretion of amyloid β (Aβ) as a result of enhanced amyloid precursor protein (APP) processing and sometimes also increased protein levels." (PMID 32611613, 2020). "In mouse fibroblasts and N2a neuroblastoma cells, β-cleavage of APP is required both for HS-anMan formation and for egress from the endosomes." (PMID 32039447, 2020). "We next evaluated the effects of GT863 on Aβ production and γ-cleavage in SH-SY5Y human neuroblastoma cells that endogenously expressed APP." (PMID 32028683, 2020). "We investigated the effects of capsaicin on brain Aβ burden and cognition in APPswe/PS1dE9 (APP/PS1) mice, and explored the underlying mechanisms in human neuroblastoma SH-SY5Y-APP695 cells and APP/PS1 mice." (PMID 32661266, 2020). "We repeatedly found that the cytokines induced formation of complexes between HS-anMan and APP degradation products, which accumulated in enlarged autophagosomes/lysosomes of dividing mouse N2a neuroblastoma and human neuronal stem cells (NSCs)." (PMID 32039447, 2020). "Posiphen has been shown to lower amyloid-beta precursor protein (APP) level in cultured human neuroblastoma cells and in mouse brain." (PMID 32058974, 2020).
neuroblastoma (continued). "How metformin stimulated A‐β peptides production was explained on cell cultures of primary cortical neurons and N2a neuroblastoma cells expressing human amyloid precursor protein (APP): metformin upregulates β‐secretase, which cleaves APP into A‐β peptides." (PMID 33392433, 2020). "In this vein, η-CTF was detected in extracellular vesicles released by N2a neuroblastoma cells expressing APP Swedish." (PMID 31607898, 2019). "In a neuroblastoma model stably overexpressing APP, we provide support that PTMs are required for the trafficking of APP to the neuronal surface and further consolidate a proposed life cycle for APP." (PMID 30796750, 2019). "A similar response, an increase in APP mRNA and a reduction in APP protein, was observed in neuroblastoma cells that were irradiated with ultraviolet (UV) light." (PMID 30744184, 2019). "Recently, the shed-off soluble matriptase was shown to cleave the APP at Arg-102 in cultured neuroblastoma cells, an event accompanied by a reduced Aβ1–40 production." (PMID 30606244, 2019). "As for TIMP-3, one study in neuroblastoma cells reported that this inhibitor not only reduces α-cleavage of APP but also the cell surface levels of ADAM10 and APP, which leads to increased endocytosis and β-secretase cleavage." (PMID 31607898, 2019). "The native, endogenously expressed APP in the M17 human neuroblastoma cells, which are a relevant model of APP processing in AD, can be quantitatively reduced when the cells expressed an active recombinant matriptase." (PMID 30606244, 2019). "Matriptase expression in the M17 human neuroblastoma cells resulted in reduction of the endogenous APP quantity." (PMID 30606244, 2019). "APN is protective against cytotoxicity of human neuroblastoma cells (SH-SY5Y) expressing mutant APP (Sw-APP) under oxidative stress through APPL1-mediated AMPK activation, associated with suppression of NF-κB activation." (PMID 31128596, 2019). "A similar observation was done in neuroblastoma cells where UV irradiation increased APP mRNA and simultaneously decreased APP protein levels." (PMID 30654492, 2019). "In amyloid precursor protein- (APP-) transfected human neuroblastoma cells, an AD cellular model with increased Aβ generation, GBE improved respiration of mitochondria, stimulated mitochondrial biogenesis, and increased ATP production." (PMID 31214285, 2019). "Overexpression of matriptase in the M17 human neuroblastoma cells was performed to determine the effect of matriptase expression on endogenous APP." (PMID 30606244, 2019). "The core histone protein H4 has been shown to have significantly higher phosphorylation levels on Serine-47 in rats with levels of APP in their neuroblastoma cells compared to rats that were null in APP for these same types of cells." (PMID 31133796, 2019). "APP overexpression reduces free iron content in neuroblastoma cells, and either preventing APP transport to the cell surface or knocking down of APP results in iron accumulation in primary cortical neurons in culture." (PMID 30837827, 2019). "In neuroblastoma cells, the myoinositol phosphate showed to inhibit beta-secretase, which produce Aβ from APP through the sequential cleavage with gamma-secretase." (PMID 31237881, 2019). "Given that bisbenzylisoquinolines are potential AD drug candidates, we examined the neuroprotective effects of DAU in a murine neuroblastoma cell line (N2a) stably transfected with the human Swedish mutant form of amyloid protein precursor (APP)." (PMID 30057671, 2018). "A similar degree of colocalisation was observed for PLD3–GFP and APP in neuroblastoma SH-SY5Y cells and PLD3–GFP was detected in endosomes positive for the retromer protein VPS35." (PMID 29368044, 2018). "Our study reveals a consistent inhibitory effect of miR-15b on the modulation of BACE1 expression in human neuroblastoma cell line and further demonstrates the role of miR-15b in the reduction in APP and Aβ levels in a human AD cell model." (PMID 29961672, 2018).
neuroblastoma (continued). "We examined the action of xanthohumol (Xn) on murine neuroblastoma N2a cells stably expressing human Swedish mutant APP, a well-characterized cellular model of AD." (PMID 29670521, 2018). "In this study, the amyloid precursor protein (APP) plasmid with Swedish and Indiana mutations was transfected into SH-SY5Y neuroblastoma cells." (PMID 28811634, 2017). "Subsequent studies, showed that overexpression of the APP protein in a neuroblastoma cell line induces mitochondrial fragmentation, probably due to increased Aβ peptide production." (PMID 28487634, 2017). "Using SILAC-based proteomic analysis, we previously demonstrated enhanced Ras expression and ERK phosphorylation upon APP expression in B103 rat neuroblastoma cells, suggesting that APP is a modulator of the proliferation-associated Ras-MAPK signaling pathway." (PMID 28374012, 2017). "In vitro nPM exposure of neuroblastoma cells (N2a-APP/swe) increased the pro-amyloidogenic processing of the amyloid precursor protein (APP)." (PMID 28140404, 2017). "Subsequent work by Masliah and colleagues demonstrated that treatment with Aβ reduced APP-Gαo interactions (corresponding to Go activation) and induced cell death in transfected neuroblastoma lines, and again this effect was PTX-dependent." (PMID 28197070, 2017). "Specifically, they found that overexpressing a membrane-tethered AICD construct (mAICD) or experimentally elevating intracellular APP-CTF levels dramatically increased neurite outgrowth in both neuroblastoma cells and transfected cortical neurons." (PMID 28197070, 2017). "More interestingly, memantine decreased the levels of secreted APP and Aβ peptide in human neuroblastoma cells and lowered cortical levels of Aβ1–42 in APP/PS1 transgenic mice." (PMID 28360837, 2017). "We find that RNA interference (RNAi)-directed knockdown of APP in B103 rat neuroblastoma cells expressing APP inhibits Ras-ERK signaling and GSK-3 activation, indicating that APP acts upstream of these signal transduction events." (PMID 28374012, 2017). "In order to model the effect of dysfunctional ESCRT-dependent MVBs on Aβ accumulation, a dominant negative, E228Q ATPase-deficient form of VPS4A (dnVPS4A) was expressed for 24 h in N2a neuroblastoma cells harbouring stably transfected human Swedish mutant APP." (PMID 28835279, 2017). "Recently, numerous studies have revealed the crucial role of APP in AD in mouse neuronal stem cells, neurons, and human neuroblastoma cell lines SH-SY5Y and La-N-1." (PMID 28659755, 2017). "This comes as a relative surprise since it has been reported that either the cotransfection of VDR or a calcitriol treatment reduces, in a dose dependent manner, APP transcription in neuroblastoma cells." (PMID 26932723, 2016). "Because ANXA1 is expressed by neurons, we investigated the effect of ANXA1 on APP processing in a neuroblastoma cell line." (PMID 27590054, 2016). "APP-GFP or AICD-GFP were co-expressed together with mCherry-ML1Nx2 in the SH-SY5Y neuroblastoma line and compared to a GFP control (Online Resource 3)." (PMID 26216398, 2016). "To characterize APP influences on endocytosis, we first analyzed N2a mouse neuroblastoma cells overexpressing wild-type human APP stably (N2aAPP)." (PMID 26194181, 2016). "Here, we performed an unbiased, comprehensive analysis of the phosphoproteome signature in APP-null neuroblastoma cells (B103) compared to those expressing APP-695 isoform (B103-695) to determine if APP expression affects protein phosphorylation." (PMID 26885753, 2016). "In neuroblastoma N2a cells expressing human APP Swedish mutant, overexpression of the SIRT1 gene increased ADAM10 protein expression." (PMID 27532339, 2016).
neuroblastoma (continued). "This study was carried out with B103 rat neuroblastoma cells that are null for or expressing the APP-695 (B103-695) isoform, using Stable Isotope Labeling by Amino Acids in Cell Culture (SILAC)-based mass spectrometry." (PMID 26885753, 2016). "N2A hippocampal neuroblastoma cells were transiently co-transfected with constructs containing mutant APP(swe)/PS1(ΔE9) and a tetracycline transactivator (TTA) as a cell-based model of effects of mutant amyloid toxicity." (PMID 25884176, 2015). "In human SH-SY5Y neuroblastoma cells, 24-OH appears to exert a unique modulatory effect on APP processing: it directly increases α-secretase activity, as well as elevating the α/β-secretase activity ratio; conversely, 27-OH enhances the generation of Aβ." (PMID 26150787, 2015). "As a cellular model for increased β-secretase processing of APP we used APPswe overexpressing human neuroblastoma cells." (PMID 26074811, 2015). "Subsequent studies demonstrated that APP and other APP metabolites are secreted within exosomes in APP-expressing neuroblastoma, confirming that MVBs are essential organelles for APP metabolism." (PMID 25741766, 2015). "PAT1a when overexpressed in neuroblastoma cells with APP, induces an increase of APP at the cell surface." (PMID 25880931, 2015). "Memantine was also shown to reduce the levels of secreted APP and Aβ both in human neuroblastoma SK-N-SH cells and in neuronal cultures and APP/PSI transgenic mice." (PMID 26697860, 2015). "In Neuro-2a, a neuroblastoma cell line that constitutively expresses APP, activation of the P2X7 receptor leads to reduction of α-secretase activity, the opposite effect being obtained by P2Y2 receptor activation." (PMID 25848496, 2015). "To exclude that the overexpression of APPswe resulted in a false-positive result, we inhibited β-secretase processing of APP in human neuroblastoma wt cells." (PMID 26074811, 2015). "CALM and APP were shown to co-localize during endocytosis in neuroblastoma N2a cells stably overexpressing APP." (PMID 25090048, 2014). "We used human SH-SY5Y neuroblastoma cells to analyze APP processing for practical reasons and experimental consistency." (PMID 24466315, 2014). "Other studies into the effect of one or both oxysterols on APP processing used the human neuroblastoma-derived cell line SH-SY5Y, except for one study employing human neural cells (HN cells) in primary culture." (PMID 24612036, 2014). "It is a neuroblastoma cell line stably transfected with amyloid precursor protein (APP)-C99 under control of a tetracycline (Tet)-repressor cassette." (PMID 24179464, 2013). "Suppression of APP expression in mice resulted in age-dependent iron accumulation, and overexpression of wild type APP resulted in iron reduction in SH-SY5Y neuroblastoma cells." (PMID 23874300, 2013). "Conversely, overexpression of APP results in reduced iron content and increased oxidative stress in human neuroblastoma cells." (PMID 23368879, 2013). "Human neuroblastoma SH-SY5Y cells with stable overexpression of wild type APP (SH-SY5Y-APP695wt) were transfected with either anti-LRRTM3 siRNA (si-LRRTM3, SASI_Hs01_00163676, Sigma) or control (si-control, SIC001 MISSION Universal Negative Control#1, Sigma)." (PMID 23750206, 2013). "Significantly decrease at the levels of C-terminal fragments of APP and the hyper-phosphorylation of APP and tau was observed in N2a mouse neuroblastoma." (PMID 24381531, 2013). "MC65 is a human neuroblastoma cell line that conditionally expresses C99, a 99-residue carboxyl terminal fragment of APP, which is subsequently cleaved by c-secretase to generate Aβ." (PMID 23750258, 2013). "These APP 5′UTRs-directed inhibitors are currently being tested as representatives of a class of intercalators that exhibit high selectivity in reducing APP production in SH-SY5Y neuroblastoma cells." (PMID 23935819, 2013). "Forced expression of PS2V in neuroblastoma cells increases γ-secretase activity and cleavage of Aβ from APP." (PMID 23805206, 2013).